VIM2P (vimentin 2, pseudogene)
Synonyms: lncRNA-CIR; RP11-162L10.1; VIM2; CIR; VIMP1
Gene: Transcribed processed pseudogene on chromosome 6 (126,602,356 to 126,603,649, reverse strand). Ensembl gene ENSG00000286215.
Diseases named in the same sentence as VIM2P in open-access papers:
VIM2P is named in the same sentence as 6 diseases in open-access papers, as found by Europe PMC text mining. Sharing a sentence is not in itself a finding about the gene and the disease.
VIM2P shares sentences with these, for which no sentence is quoted: Arthritis (1 paper); bladder cancer (1); cancer (1); cystic fibrosis (1); melanoma (1); tumor (1).